TXNDC12 (thioredoxin domain containing 12)
Diseases named in the same sentence as TXNDC12 in open-access papers (continued):
Sharing a sentence is not in itself a finding about the gene and the disease.
tumor (15 papers, 2015 to 2025). "The first was a group of novel genes and the second was a group of genes associated with various cancer and tumour diseases (TXNDC12, NRDC, MIR761, ITSN2, NCOA1, SCUBE2, DENND5A, RCN2)." (PMID 40003092, 2025). "For example, the expression level of TXNDC12 mRNA in gastric, liver, and other tumor tissues is significantly higher than that in non-tumor tissues and is significantly associated with poor prognosis of patients." (PMID 34629960, 2021). "As TXNDC12 has been implicated in regulating tumor aggressiveness, we next investigated whether its depletion would potentiate the inhibitory effects of cisplatin in HNSCC cells." (PMID 40750708, 2025). "Importantly, aberrant expression of TXNDC12 has been associated with tumor progression and poor prognosis in several malignancies." (PMID 40750708, 2025). "However, high TXNDC12 expression in late-stage tumors is significantly associated with poor survival (p = 0.00087), confirming its role in tumor metastasis." (PMID 37128318, 2023). "Given that TXNDC12’s tumor-promoting effects are largely mediated through c-Myc, it is logical that depleting TXNDC12 leads to profound changes in tumor cell phenotypes both in vitro and in vivo." (PMID 40750708, 2025). "Modulating TXNDC12 levels demonstrates that its reduction curtails aggressive tumor phenotypes and cisplatin resistance, while its overexpression exacerbates these characteristics." (PMID 40750708, 2025). "Our study reveals pronounced overexpression of TXNDC12 in HNSCC, associated with enhanced tumor aggressiveness and poor prognosis." (PMID 40750708, 2025). "Our findings indicate that TXNDC12 not only promotes tumor aggressiveness but also plays a role in modulating the cellular response to cisplatin." (PMID 40750708, 2025). "This study underscores the pivotal role of TXNDC12 in modulating tumor biology and chemoresistance, positioning the METTL1-TXNDC12-c-Myc axis as a promising target for improving patient outcomes in HNSCC." (PMID 40750708, 2025). "Compared to the control group, the knockdown of TXNDC12 resulted in a 3-fold increase in IKE-induced tumor suppression, which was further inhibited by the ferroptosis inhibitor liproxstatin-1." (PMID 38047088, 2023). "Specifically, through protein-protein interaction, TXNDC12 can activate β-catenin and facilitate the epithelial-mesenchymal transition process, thereby promoting tumor metastasis." (PMID 38047088, 2023). "ZC3H13 was mainly expressed in smooth muscle cells, fibroblasts, and TXNDC12 was mainly expressed in tumor/epithelial cells, macrophages, and endothelial cells." (PMID 36712973, 2022). "The results showed that in the group with high TXNDC12 expression, tumor cell purity in tumor tissues decreased, immune cells, and extracellular matrix increased, and mast cell activity decreased." (PMID 34629960, 2021). "The protein levels of TXNDC12 were significantly higher in PVTT tissues than in their counterpart tumor tissues." (PMID 31570854, 2020). "Overexpression of TXNDC12 in HCC is a strong indicator of high tumor aggressiveness and correlates with poor clinical outcomes." (PMID 31570854, 2020). "Notably, TXNDC12 expression levels were significantly elevated in tumor tissues relative to precancerous lesions in the GSE85195 and GSE30784 datasets." (PMID 40750708, 2025). "Furthermore, IHC analysis of tumor sections revealed a lower proportion of Ki-67-positive cells in tumors formed from HNSCC cells with TXNDC12 depletion, indicating reduced proliferative activity." (PMID 40750708, 2025). "The results indicated a significant increase in TXNDC12 expression in tumor tissues." (PMID 40750708, 2025). "Notably, in a nude mouse subcutaneous tumor model, there were significant reductions in both tumor volume and weight in the group with TXNDC12 depletion compared with the control group." (PMID 40750708, 2025).
tumor (continued). "Given that TXNDC12 enhances c-Myc expression at the post-transcriptional level, we investigated whether TXNDC12’s tumor-promoting role in HNSCC cells is primarily mediated by c-Myc." (PMID 40750708, 2025). "Targeting this TXNDC12-dependent resistance mechanism could enhance ferroptosis-induced tumor suppression." (PMID 38047088, 2023). "Similarly, the protein levels of TXNDC12 were higher in HCC lung metastases than in their counterpart tumor tissues." (PMID 31570854, 2020). "As a tumor-related gene, TXNDC12 may be used as a new prognostic judgment molecule." (PMID 34629960, 2021). "In vivo experiments demonstrated that TXNDC12 overexpression significantly enhanced the tumorigenic capacity of HNSCC cells, as evidenced by increased tumor volume and weight in a nude mouse model." (PMID 40750708, 2025). "After systematic data curation, four upregulated (YWHAB, TXNDC12, MYL6B, SFN) and four downregulated (FN1, PSMB6, PRDX4, PEA15) markers in miRNA-overexpressed tumor secretomes were identified." (PMID 37128318, 2023). "Here, we showed that TXNDC12, a thioredoxin-like protein, was upregulated in highly metastatic HCC cell lines as well as in portal vein tumor thrombus and lung metastasis tissues of HCC patients." (PMID 31570854, 2020). "To further explore the role of TXNDC12 in HCC metastasis, we first compared the expression levels of TXNDC12 between PVTT tissues and the corresponding patient-matched primary tumor tissues." (PMID 31570854, 2020).
cancer (12 papers, 2020 to 2025). A tumor composed of atypical neoplastic, often pleomorphic cells that invade other tissues. "The potential prognostic value of TXNDC12 was also assessed in other cancer types using data from TCGA." (PMID 40750708, 2025). "Colony formation assays demonstrated that combining TXNDC12 depletion with cisplatin significantly reduced the colony-forming capacity of the cancer cells more than any single treatment." (PMID 40750708, 2025). "Functionally, we demonstrate that targeting TXNDC12 can effectively enhance the sensitivity of cancer cells to erastin or RSL3-induced ferroptosis." (PMID 38047088, 2023). "In this study, we present an antioxidant mechanism involving ER-related TXNDC12 in human cancer cells." (PMID 38047088, 2023). "Thioredoxin domain-containing 12 (TXNDC12) has been shown to play an important role in various malignant tumors." (PMID 34629960, 2021). "Considering c-Myc’s status as ‘difficult-to-drug’ or ‘undruggable’27, our findings highlight the targeting of TXNDC12 as a novel and effective approach to circumvent the challenges posed by c-Myc in cancer therapy, underscoring the importance of this strategy in advancing cancer treatment." (PMID 40750708, 2025). "Previous studies have shown that TXNDC12 is highly expressed in a variety of tumors 19-21, so we first analysed the expression of TXNDC12 in pan-cancer and the results showed that TXNDC12 expression levels were up-regulated in tissues of most cancer types, including PAAD, compared to normal tissues." (PMID 38911386, 2024). "Thioredoxin domain-containing protein 12 (TXNDC12), which is also known as ERp16, ERp18, ERp19, or hTLP19, is a member of the protein disulfide isomerase (PDI) family that plays important roles in cancer development and progression." (PMID 31570854, 2020). "Immunohistochemistry (IHC) staining of our in-house HNSCC cohort revealed that TXNDC12 staining intensity was significantly higher in patients with lymph node metastasis, advanced TNM stage or poorly differentiated carcinoma compared with their corresponding controls." (PMID 40750708, 2025). "Although the role of TXNDC12 in cancer is not extensively documented, studies suggest its potential involvement in cancer progression and cellular responses to oxidative stress." (PMID 38047088, 2023). "Moreover, several studies have confirmed the cancer‐promoting effects of PDIA5 and TXNDC12 as important contributors to cancer progression and chemoresistance." (PMID 32301283, 2020). "TXNDC12 has also not been identified in OMICS screens of human cancer until recently." (PMID 35965326, 2022).
TXNDC12 also shares sentences with these, for which no sentence is quoted: infection (3 papers); acute myeloid leukemia (1); Arterial thrombosis (1); breast tumours (1); cervical squamous cell carcinoma (1); dilated cardiomyopathy (1); esophageal carcinoma (1); liver cancer (1); lung carcinoma (1); mesothelioma (1); pancreatic ductal adenocarcinoma (1); sarcoma (1); Sepsis (1); thrombosis (1); thrombotic disease (1); thyroid carcinoma (1); uveal melanoma (1); viral myocarditis (1).